ENSG00000289763 (novel protein)
Gene: Protein-coding gene on chromosome 3 (10,249,042 to 10,249,366, forward strand). Ensembl gene ENSG00000289763.
Homologues: Orthologues: mouse Gm63648 (82% identical).